SAA4 (serum amyloid A4, constitutive)
Description:
Major acute phase reactant.
Synonyms: C-SAA; CSAA
Tractability: Antibody: UniProt places it where antibodies can reach, with medium confidence; UniProt predicts a signal peptide or a membrane-spanning region; its Gene Ontology location is reachable by antibodies, with medium confidence. PROTAC: its protein half-life has been measured.
Gene: Protein-coding gene on chromosome 11 (18,231,344 to 18,236,860, reverse strand). Ensembl gene ENSG00000148965.
Subcellular location: Secreted
Gene Ontology:
Molecular function: protein binding
Cellular component: extracellular exosome; extracellular region
Genetic constraint (gnomAD): Loss-of-function variants: 7 observed, 9.39 expected, observed/expected ratio (o/e) 0.75, 90% interval 0.42 to 1.39. That is too few expected variants to judge how well the gene tolerates losing a copy. Missense variants: 118 observed, 117.62 expected, observed/expected ratio (o/e) 1, 90% interval 0.86 to 1.17. Synonymous variants: 44 observed, 36.49 expected, observed/expected ratio (o/e) 1.21, 90% interval 0.95 to 1.55.
Homologues: Orthologues: chimpanzee SAA4 (98% identical), macaque SAA4 (84% identical), rabbit SAA4 (66% identical), rat Saa4 (59% identical), mouse Saa4 (58% identical), zebrafish saa (43% identical), Drosophila melanogaster CG30467 (8% identical). Paralogues in human: SAA1 (52% identical), SAA2 (52% identical), SAAL1 (22% identical).
Diseases named in the same sentence as SAA4 in open-access papers:
SAA4 is named in the same sentence as 43 diseases in open-access papers, as found by Europe PMC text mining. Sharing a sentence is not in itself a finding about the gene and the disease. The quoted sentences say what the papers report.
COVID-19 (5 papers, 2021 to 2024). A disease caused by infection with severe acute respiratory syndrome coronavirus 2. "For example, acute phase proteins (APPs) including serum amyloid A-1 (SAA1), SAA2, SAA4 and C-reactive protein (CRP) were increased in severe COVID-19 patients, indicating activation of inflammation and the complement system." (PMID 35686122, 2022). "The acute phase response proteins such as SAA-4 and S100A8 were also upregulated in response to COVID-19." (PMID 33995121, 2021). "Further, the deep plasma proteome study of non-severe versus severe COVID-19 patients revealed only 38 differentially expressed proteins, out of which proteins such as FGG, S100A8, VWF, SAA4, SERPIND1, and SERPINA6 were identified to be significantly upregulated in the COVID-19 severe patients." (PMID 33995121, 2021). "Moreover, most acute phase proteins, such as SAA1, SAA2, SAA4, CRP, SERPINA3, and SAP/APCS, which were increased in severe COVID-19 patients were not changed in our CoronaVac immunized samples." (PMID 35686122, 2022).
Ovarian cyst (3 papers, 2012 to 2018). The presence of one or more cysts of the ovary. "In our study, SAA4 was up-regulated in ovarian cyst fluid from patients with malignant tumors, which is consistent with validated SELDI-TOF MS in serum from ovarian cancer patients." (PMID 23268721, 2012). "Finally, the study of ovarian cyst fluid allowed to select SAA4 as a possible ovarian-tumor-specific biomarker." (PMID 30065196, 2018).
ovarian tumor (3 papers, 2012 to 2020). "Firstly, we examined the expression of SAA-1, SAA-2, and SAA-4 in ovarian tumor tissues and OVCAR-3 cells." (PMID 32517794, 2020). "A study of ovarian tumors showed a direct correlation between serum levels, intracellular expression of SAA4 and malignant state of the epithelial cells." (PMID 23268721, 2012). "We found that SAA-1 and SAA-4 could be expressed in ovarian tumor tissues and OVCAR-3 cell, but SAA-2 could not." (PMID 32517794, 2020).
rheumatoid arthritis (3 papers, 2017 to 2020). A chronic, systemic autoimmune disorder characterized by inflammation in the synovial membranes and articular surfaces. "ORM2 was founded to be associated with microglial interaction, SAA4 was identified as a rheumatoid arthritis-screening biomarker, and MAP2K6 was reported to be involved in the pathogenesis of colorectal adenocarcinoma." (PMID 32130204, 2020). "The range of expression levels of SAA4 and VDBP was wide in rheumatoid arthritis patients, although the expression of these biomarkers was higher in the rheumatoid arthritis patients than in the control group." (PMID 31491989, 2019).
atherosclerosis (2 papers, 2021 to 2025). A disease characterized by the build-up of fatty material and calcium deposition in the arterial wall resulting in partial or complete occlusion of the arterial lumen. "SAA4 is a major acute phase reactant expressed in coronary artery macrophages, which suggests that SAA4 plays a special role in inflammatory processes including atherosclerosis." (PMID 34746269, 2021). "An important role in the pathogenesis of atherosclerosis is played by the genes ALB, SHBG, APOC, APOC3, APOC4, and SAA4, of which APOC3 and APOC4 make a major contribution to the occurrence of atherosclerosis and also to insulin resistance and type 2 diabetes." (PMID 40361926, 2025).
cyst (2 papers, 2012 to 2013). A sac-like closed membranous structure that may be empty or contain fluid or amorphous material. "A group of 68 cyst fluids of heterogeneous histology were subsequently analysed by immunoblot, and the divergence remained between the groups (p = 0.001), which suggests SAA4 as a potential novel biomarker." (PMID 23557354, 2013). "The cyst fluid from patients with malignant disease displayed a significantly higher expression of SAA4 (p = 0.001) compared to the benign samples, confirming the results from the iTRAQ analysis where the SAA4 expression levels also differed significantly (p = 0.001)." (PMID 23557354, 2013). "The peaks with highest ROC AUC for each protein in cyst fluid (PCI, ApoC-III, ApoC-I, SAA4 and TTR) were selected for further statistical analysis together with corresponding serum CA125." (PMID 23268721, 2012). "Two proteins, serum amyloid A-4 (SAA4) and astacin-like metalloendopeptidase (ASTL), were selected for verification of the iTRAQ method and external validation with immunoblot in a larger cohort with mixed histology, in plasma (n = 68), and cyst fluid (n = 68)." (PMID 23557354, 2013). "Among the 68 cyst fluids used in the external validation set, two benign serous adenomas and five serous adenocarcinomas of different stages were identical with the iTRAQ sample set and demonstrated good correlation for the SAA4 expression (p = 0.008; data not shown)." (PMID 23557354, 2013).
lung carcinoma (2 papers, 2021 to 2025). "Based on these results, seven proteins, CD5L, CLEC3B, SERFINF1, ITIH4, SAA4, SERFINC1, and C20ORF3 (AMAP) were confirmed as being upregulated in EVs and were therefore considered as potential lung cancer biomarkers." (PMID 33808296, 2021). "In addition, CLEC3B, ITIH4, SERFINF1, SAA4, SERFINC1, and C20ORF3, whose expression was significantly increased in EVs derived from lung cancer patients, can be included as potential biomarkers." (PMID 33808296, 2021).
ovarian carcinoma (2 papers, 2012 to 2013). A malignant neoplasm originating from the surface ovarian epithelium. "We had therefore several reasons why SAA4 is an interesting choice for further evaluation as a potential biomarker in ovarian cancer." (PMID 23557354, 2013).
periodontitis (2 papers, 2016 to 2019). An acute or chronic inflammatory process that affects the tissues that surround and support the teeth. "In addition, we found enrichment of the common SAA4 form, and decreased expression of one glycosylated SAA4 form, which suggests redistribution of the protein in HDL in periodontitis." (PMID 30842338, 2019).
bacterial sepsis (1 paper, 2025). "SAA-/- mice carrying a deletion of the Saa1, Saa2, Saa3, and Saa4 serum amyloid A genes have better survival rates in sterile sepsis but are more prone to bacterial sepsis than their SAA+/+ counterparts, emphasizing their dual functionality in immune regulation." (PMID 40061939, 2025).
basal cell carcinoma (1 paper, 2024). A carcinoma involving the basal cells. "However, in the low SAA4 expression group, the DEGs were mainly involved in basal cell carcinoma, cardiac muscle contraction, dilated cardiomyopathy, ECM receptor interaction and neuroactive ligand receptor interaction." (PMID 38300370, 2024).
colon cancer (1 paper, 2012). "In colon cancer SAA4 levels increases gradually from epithelial dysplasia to cancer in tissue samples and are highest in metastatic cancer, which supports the possibility of its role in carcinogenesis." (PMID 23268721, 2012).
colorectal cancer (1 paper, 2025). A primary or metastatic malignant neoplasm that affects the colon or rectum. "Notably, several significantly altered proteins, including APOA4, CLU, and SAA4, have previously been reported as potential biomarkers for colorectal cancer." (PMID 41367384, 2025).
endometrial cancer (1 paper, 2022). Primary or metastatic malignant neoplasm involving the endometrium (mucous membrane that lines the endometrial cavity). "Quantification analysis in 36 patients with endometrial cancer compared to 36 healthy individuals confirmed the upregulation of APOA1, HBB, CA1, HBD, LPA, SAA4, PF4V1, and APOE." (PMID 36551747, 2022).
epithelial ovarian tumors (1 paper, 2017). "SAA4 is expressed in graft-versus-host disease (GVHD) and epithelial ovarian tumors; however, to the best of our knowledge, this is the first report describing SAA4 expression in RA." (PMID 28505104, 2017).
glioma (1 paper, 2013). A benign or malignant brain and spinal cord tumor that arises from glial cells (astrocytes, oligodendrocytes, ependymal cells). "Because SAA is an acute-phase protein predominantly expressed and produced in the liver in response to inflammation, we tested whether these glioma cells express and produce the isoforms SAA1, SAA2, and SAA4 in basal conditions." (PMID 23533307, 2013).
glomerulosclerosis (1 paper, 2024). A hardening of the kidney glomerulus caused by scarring of the blood vessels. "Interestingly, glomerulosclerosis showed a significant positive correlation with 15 proteins, including SAA4 (= 0.346) and C3 (= 0.435)." (PMID 39835101, 2024).
malaria (1 paper, 2025). Malaria is a serious and sometimes fatal disease caused by a parasite that commonly infects a certain type of mosquito which feeds on humans. "In contrast to Saa1 and Saa2, the genes Saa3 and Saa4 displayed significantly lower constitutive expressions of about 90 and 178, respectively, and their malaria-responsive expression profiles responded to vaccination, though differently." (PMID 40243929, 2025).
metabolic syndrome (1 paper, 2014). A cluster of metabolic risk factors for CARDIOVASCULAR DISEASES and TYPE 2 DIABETES MELLITUS. "Finally, glycosylated isoform of SAA4 in HDL fraction was 42% lower in patients with metabolic syndrome compared with controls (p<0.001)." (PMID 25118169, 2014).
mucinous adenoma (1 paper, 2013). "SAA4 levels were low in simple cysts, mucinous adenoma and all six mucinous carcinomas." (PMID 23557354, 2013).
Obesity (1 paper, 2022). Accumulation of substantial excess body fat. "The contributions of SAA4 if any, to obesity and glucose homeostasis need to be investigated in future." (PMID 35436297, 2022).
preeclampsia (1 paper, 2025). Preeclampsia is a hypertensive disorder of pregnancy that is characterized by new-onset hypertension with proteinuria presenting after 20 weeks of gestation, and depending on mild or severe forms may initially present with severe headache, visual disturbances, and hyperreflexia. "SAA4 has been implicated in inflammation and oxidative stress, which are key factors in preeclampsia." (PMID 40974471, 2025). "Additionally, SAA4, ANG, CFHR5, IGKV3-7, and PAPPA have been suggested to play a role in the context of preeclampsia." (PMID 40974471, 2025). "Investigating similar interactions for SAA4 and ANG may uncover new regulatory networks in CL function and preeclampsia." (PMID 40974471, 2025).
small cell lung carcinoma (1 paper, 2022). Small cell lung cancer (SCLC) is a highly aggressive malignant neoplasm, accounting for 10-15% of lung cancer cases, characterized byrapid growth, and early metastasis. "The expression levels of seven proteins (CD5L, CLEC3B, SERFINF1, ITIH4, SAA4, SERFINC1, and C20ORF3 (APMAP)) were found to be significantly increased in serum-derived EVs of lung cancer patients, including AC, SCC, and small cell lung cancer (SCLC)." (PMID 35158999, 2022).
cancer (10 papers, 2012 to 2024). A tumor composed of atypical neoplastic, often pleomorphic cells that invade other tissues. "High expression level of SAA4 predicted a worse prognosis in OS among cancers including CHOL, KIRC, KIRP, LGG, OV and PAAD." (PMID 38659199, 2024). "We found that the mRNA of SAA-1 and SAA-4 was much higher in cancer tissues than in adjacent tissues by qRT-PCR." (PMID 32517794, 2020). "To confirm whether SAA4 display a consistent biological role among cancer, we performed GSEA analysis across cancers." (PMID 38659199, 2024). "Moreover, SAA is an acute-phase protein family, and we observed that SAA1, SAA2, and SAA4 protein levels increased significantly as cancer progressed." (PMID 37209815, 2023). "The quantitative Reverse transcription polymerase chain reaction (qRT-PCR) assay revealed that the Messenger RNA (mRNA) of SAA-1 and SAA-4 was much higher in cancer tissues than in adjacent tissues, and MMPs was up-regulation including MMP-1, MMP-9 and MMP- 12 in OVCAR-3 cell stimulated by SAA." (PMID 32517794, 2020). "Among them, a gradual increase from early-stage cancer to more advanced stages were strongest for APOC2 and IL8 genes followed by for SAA4 and OSM genes, whereas HIST1H1E, PF4V1, CXCL5, and IL2RA expression showed limited stage-wise upregulation." (PMID 33828156, 2021). "We wonder if it would be possible to label an antibody for SAA4 with a nuclide and then screen the patient with PET or some other equipment and be able to verify the presence of a malignant tumor as opposed to a benign cyst." (PMID 23557354, 2013).
infection (6 papers, 2018 to 2025). The state of being infected such as from the introduction of a foreign agent such as serum, vaccine, antigenic substance or organism. "Overexpression of Saa1, Saa2, Saa3, and Saa4 in macrophages enhances NF-κB-mediated pro-inflammatory cytokine production and bacterial clearance during infection." (PMID 40061939, 2025). "Serum amyloid A (SAA) subtypes 1–3 are well-described acute phase reactants that are elevated in acute inflammatory conditions such as infection, tissue injury, and trauma, while SAA4 is constitutively expressed." (PMID 37396595, 2023).
tumor (5 papers, 2013 to 2024). "Aided by proteogenomic datasets, we found that SSA4 was highly expressed in tumor tissues and late-stage patients and validated the aberrant SAA4 expression level in patient serum by ELISA, which was also detected at the transcriptome level." (PMID 38659199, 2024). "Combining the results of survival analysis based on the TCGA and K‒M plotter databases, we found that high SAA4 expression in tumor tissues was closely related to good outcomes in HCC." (PMID 38300370, 2024). "In the IHC staining analysis, the SAA4 protein expression in normal tissues was higher than that in tumor tissues according to the results from the THPA." (PMID 38300370, 2024). "First, we compared the gene expression of SAA4 between tumor and paracancerous tissues." (PMID 38300370, 2024). "In addition, the expression of SAA4 was also significantly lower in tumor tissues than in normal tissues in the paired analysis." (PMID 38300370, 2024). "In addition, the concentrations of SAA4 increased gradually with tumor progression and the severity of BC stages." (PMID 33182810, 2020). "Interestingly, the increasing levels of SAA4 in relation to tumor progression (stage I – stage III) were detected both in the present study and in our SELDI-TOF MS investigation." (PMID 23557354, 2013). "However, it is unclear whether SAA4 plays a critical role in the progression of tumor such as HCC." (PMID 38300370, 2024). "WB analysis of serum and tumor tissue specimens confirmed the upregulation of eight proteins: APOA1, HBB, CAH1, HBD, LPA, SAA4, PF4V1, and APOE." (PMID 39194522, 2024). "The results showed that unlike the traditional biomarkers, SAA4 was significantly downregulated in tumor tissues versus paracancerous tissues." (PMID 38300370, 2024). "In addition, SAA4 may be helpful for the diagnosis of early HCC and may become a novel tumor marker with good predictive power for HCC." (PMID 38300370, 2024).
bacterial infection (1 paper, 2025). "To examine the expression patterns of SAA isoforms under different inflammatory conditions, we measured SAA1, SAA2, SAA3, and SAA4 levels in SAA+/+ mice across three experimental groups: healthy controls, LPS-treated (sterile inflammation), and P. aeruginosa-infected (bacterial infection)." (PMID 40061939, 2025).
SAA4 also shares sentences with these, for which no sentence is quoted: amyloidosis (3 papers); Arthritis (1); bladder cancer (1); colorectal adenocarcinoma (1); depression (1); dilated cardiomyopathy (1); epithelial dysplasia (1); esophageal cancer (1); graft versus host disease (1); metastatic cancer (1); mucinous carcinomas (1); mucinous tumors (1); rheumatic diseases (1); septic arthritis (1); serous adenocarcinoma (1); triple-negative breast carcinoma (1).